GPX4 (glutathione peroxidase 4)
Diseases named in the same sentence as GPX4 in open-access papers (continued):
Sharing a sentence is not in itself a finding about the gene and the disease.
lung cancer (continued). "The group of Zhou and colleagues demonstrated that orlistat decreases GPX4 and increases lipid peroxidation, promoting ferroptosis in lung cancer cells." (PMID 37416772, 2023). "Inhibition of GPX4 by siRNA transfection decreased cell viability of A549 and H1975 cells in the MPE of LCP compared with lung cancer cells transfected with control siRNA, whereas ectopic expression of GPX4 prevented cell death induced by MPE in HCC827 cells." (PMID 37649596, 2023). "In the lung cancer cell line A549, the deubiquitinase inhibitor PdPT increases the ubiquitination of GPX4 and promotes the protein degradation of GPX4." (PMID 36369321, 2023). "According to the current research content, the targets of ferroptosis in lung cancer mainly focus on the regulation of antioxidant pathways, among which GPX4 and SLC7A11 are the core targets of the GSH-dependent antioxidant pathway." (PMID 37005430, 2023). "In this study, we demonstrated the chemotherapeutic agent etoposide can induce ferroptosis in lung cancer cells in a GPX4-dependent manner." (PMID 37188685, 2023). "At the same time, inhibition of GPX4 expression can partially reduce the radiation resistance of lung cancer cells and promote the efficacy of radiotherapy." (PMID 37005430, 2023). "MPE collected from lung cancer patients with pleural metastasis stimulated the expressions of GPX4, FTL, and NUPR1, whereas decreased the expression of ACSL4 in both A549 and H1975 cells." (PMID 37649596, 2023). "Fuzheng Kangai Decoction (FZKA) can induce ferroptosis of lung cancer cells by inhibiting GPX4, increasing lipid peroxidation and cellular Fe2+ level, and inhibit tumor growth in vivo." (PMID 37005430, 2023). "Knockdown of Notch3 can increase the ROS level in lung cancer cells, reduce the expression levels of GPX4 and peroxiredoxin 6 (PRDX6), and then induce lipid peroxidation to trigger cell ferroptosis." (PMID 37005430, 2023). "IHC results also showed that the level of GPX4 was higher in pleural tumor cells than in primary cancer cells in matched specimens from lung cancer patients." (PMID 37649596, 2023). "Here, we report for the first time that the difference in etoposide sensitivity between different type of lung cancer cells is partly due to its resistance to ferroptosis, which is mediated by GPX4, a key enzyme controlling lipid peroxide homeostasis." (PMID 37188685, 2023). "In terms of mechanism, isoorientin acts as a modulator that controls the SIRT6/NRF2/GPX4 signaling pathway (downregulation of the expression of SIRT6 protein, NRF2, and GPX4), thereby regulating ferroptosis and reversing drug resistance in lung cancer cells." (PMID 37760042, 2023). "Platinum resistance is more likely to develop in lung cancer brain metastases through a mechanism that reduces ferroptosis by upregulating glutathione peroxidase 4 (GPX4) expression and inhibiting GSH depletion via the Wnt/NRF2/GPX4 axis." (PMID 37736551, 2023). "Downregulation of GPx4 or the use of a FIN targeting GPx4 improves the sensitivity of radiation-resistant lung cancer cells after high-dose and low fractionation IR." (PMID 37007068, 2023). "Taken together, our data strongly suggest that GPX4 dictates sensitivity to ferroptosis induction by etoposide in lung cancer cells." (PMID 37188685, 2023). "Apart from natural compounds, some drugs that have been marketed such as Vorinostat, Orlistat have also been found to act as ferroptosis inducers in lung cancer cells via inhibiting System Xc−/GSH/GPX4 axis." (PMID 36105219, 2022). "GPX4 promotes proliferation and ferroptosis resistance in lung cancer, while GPX4 inhibitor RSL3 limits proliferation, migration, and invasion of cisplatin-resistant A549 cells." (PMID 36105219, 2022). "In NSCLC, recent reports suggest that human lung cancer cell growth can be inhibited by GPX4-related ferroptosis, a type of cell death characterized by lethal accumulation of lipid-based ROS17,18." (PMID 36443446, 2022).
lung cancer (continued). "When the GPX4 gene of lung cancer cells is deleted, FSP1 would be modified by myristoylation, and CoQ10 is reduced by NAD (P) h to produce radial trapping antioxidants (RTA) to prevent lipid peroxidation and inhibit ferroptosis." (PMID 35252001, 2022). "STYK1 shows carcinogenicity by increasing the expression of GPX4 and then controlling ferroptosis in lung cancer cells." (PMID 35875069, 2022). "The broad-spectrum DUB inhibitor palladium pyrithione was also able to induce ferroptosis by promoting GPX4 protein degradation in lung cancer cells, while erastin promoted the UPS-dependent degradation of VDAC2 and VDAC3 during ferroptosis in melanoma cells." (PMID 36358651, 2022). "In lung cancer, the presence of FSP1 maintains the growth of lung cancer cells when GPX4 is inactivated, so an apparent targeting of FSP1 seems to be a new target for cancer therapy, the study said." (PMID 36387147, 2022). "Overexpression of GPX4 promoted the proliferative capacity of lung cancer cells and inhibited ferroptosis, whereas RSL3 hindered GPX4 activity and limited the proliferation, migration, invasion, and angiogenesis of lung cancer cells." (PMID 35813823, 2022). "High expression of serine-threonine tyrosine kinase 1 (STYK1) in NSCLC cell line SW900 promotes the expression of GPX4 and the proliferation of lung cancer cells." (PMID 34630843, 2021). "The expression of GPX4 downstream was also significantly lower in AFC-treated lung cancer cell lines than in control cells." (PMID 33746607, 2021). "The results showed a significant positive correlation between cystine and GPX4; this indicated a vital role of GPX4 in the glutathione metabolism‐related ferroptosis in lung cancer BM." (PMID 34586745, 2021). "Further research found that after high expression of FSP1 in H460 lung cancer cells, the cells can still survive normally after knocking out GPX4, whereas rapid death was observed in GPX4 and FSP1 double-knockout cells." (PMID 34576065, 2021). "Meanwhile, considering the effect of endogenous GPX4 expression, two lung cancer cell lines with GPX4 high-expression NCI-H1299 and NCI-H661 were used as positive control." (PMID 33746607, 2021). "Subsequent mechanistic studies have shown that overexpression of STYK1 up-regulates expression of GPX4 protein, resulting in decreased sensitivity of lung cancer SW900 cells to ferroptosis." (PMID 34742351, 2021). "Our findings indicated a central role of GPX4 in mediating platinum resistance in lung cancer BM cells." (PMID 34586745, 2021). "Our findings provide new insights into the application of concomitant detection of cystine and GPX4 in clinical settings to assess the chemotherapeutic response of lung cancer patients with BM." (PMID 34586745, 2021). "Dietary supplementation of antioxidants or genetic manipulation of cells to increase glutathione synthesis (will also increase GPX4 activity) has been shown to promote distant metastasis in animal models of lung cancer and melanoma." (PMID 34429409, 2021). "GPX4 inhibitor was found to augment the anticancer effect of platinum drugs in lung cancer BM, providing novel strategies for lung cancer patients with BM." (PMID 34586745, 2021). "Other studies have found that cisplatin-induced ferroptosis of lung cancer cells is further enhanced by the GPX4 inhibitor RSL3 or the bioflavonoid ginkgolide in an autophagy-dependent manner." (PMID 34742351, 2021). "Further we determined the correlation between the levels of cystine and GPX4 in lung cancer patients with BM; this suggests a close relationship between the metabolism of GPX4 and GSH in BM." (PMID 34586745, 2021). "The circAFF4/USP10/GPX4 axis provides a new direction and may be a potential target for lung cancer treatment." (PMID 42010438, 2026).
lung cancer (continued). "A deeper understanding of the molecular mechanisms of lung cancer can help develop therapeutic strategies targeting GPX4 that can become an essential component of personalized treatment, offering novel prospects to enhance treatment efficacy and survival rates for patients with lung cancer." (PMID 40191731, 2025). "Therefore, we propose that reduced NLN levels lead to diminished m6A modification of GPX4, resulting in GPX4 mRNA instability and subsequently triggering ferroptosis in lung cancer cells." (PMID 41242017, 2025). "GPX4 is one of the essential regulators of ferroptosis in gastric cancer, clear cell carcinoma (often occurring in the kidneys and ovaries), and lung cancer." (PMID 39858464, 2025). "In a lung cancer H460 xenograft model, the simultaneous inhibition of GPX4 and FSP1 was necessary to suppress tumor growth, suggesting that therapies targeting GPX4 alone might fail due to the compensatory activation of FSP1." (PMID 40862825, 2025). "For instance, bufotalin, a natural small molecule, acts as a promising GPX4 inhibitor, facilitating GPX4 ubiquitination and increasing intracellular Fe2+ levels and lipid peroxidation, thereby promoting ferroptosis and inhibiting lung cancer." (PMID 38519984, 2024). "They found that SLC7A11 and GPX4 are dysregulated in many types of cancers and may serve as candidate prognostic biomarkers, such as colorectal cancer and lung cancer." (PMID 37807410, 2023). "Experiments with H460 lung cancer cells revealed that the expression of FSP1 could maintain the growth of lung cancer cells when GPX4 was inactivated." (PMID 38161691, 2023). "Moreover, high SLC7A11 levels increased cystine absorption, promoted GSH synthesis, increased GPX4 activity, enhanced the antioxidant capacity of lung cancer cells, inhibited lung cancer cell ferroptosis, and promoted cancer development." (PMID 37056388, 2023). "In the study of lung cancer, the immunohistochemical staining results of clinical lung adenocarcinoma samples compared with normal alveolar epithelial cells and bronchial epithelial cells showed that GPX4 was strongly positive in lung adenocarcinoma tissues." (PMID 37005430, 2023). "Additionally, a protein called STYK1 has been identified in lung adenocarcinoma cells, which promotes lung cancer metastasis and suppresses ferroptosis through upregulating GPX4 expression." (PMID 37946181, 2023). "The research based on the inhibition of ferroptosis by the antioxidant enzyme SLC7A11/GPX4 axis may be a breakthrough in the treatment of lung cancer." (PMID 37266741, 2023). "Meanwhile, another kind of cryptotanshinone (CTS) extracted from the rhizome of Salvia miltiorrhiza Bunge can not only prevent pulmonary fibrosis, but also promote ferroptosis of lung cancer by inhibiting GPX4 activity, and activate caspase-3 to promote apoptosis of lung cancer." (PMID 37005430, 2023). "In conclusion, GPX4 can affect the development of lung cancer by regulating ferroptosis." (PMID 37005430, 2023). "Here, we identified a novel GPx4 inhibitor, PB, a dioscin isolated from Paris formosana Hayata plants, which has been used as the main component of traditional anticancer medicine for treating lung cancer, gastric cancer and other tumours." (PMID 36923926, 2023). "However, little is known about how the expression of GPX4 is regulated by chemotherapeutic agent in lung cancer cells." (PMID 37188685, 2023). "GPX4, an antioxidant enzyme, may play an important role in carcinogenesis in the context of lung cancer." (PMID 36443446, 2022). "Further study is required to understand this context-dependent effect on GPX4 in lung cancer cells." (PMID 35459868, 2022). "In conclusion, GSTP1 may be a novel negative regulator of ferroptosis other than GPX4, may play an important role in lung cancer radiotherapy by inhibiting ferroptosis." (PMID 36589232, 2022).
lung cancer (continued). "Moreover, small molecules activating ferroptosis through System Xc− inhibition or GPX4 inhibition enhance the antitumor effect of radiotherapy and photodynamic therapy in lung cancer." (PMID 36105219, 2022). "Targeting the GPX4 pathway may provide a new strategy for treating lung cancer growth and metastasis." (PMID 35813823, 2022). "GPX4 inhibitor could augment the anticancer effect of platinum drugs in lung cancer brain metastasis." (PMID 35236309, 2022). "For instance, Tang and his coworkers revealed that curcumin administration led to iron overload, glutathione (GSH) depletion, and lipid peroxidation, causing the downregulation of Recombinant Solute Carrier Family 7, Member 11, and Glutathione peroxidase 4 (GPX4) in lung cancer cells." (PMID 36558995, 2022). "It has been reported that glutathione metabolism in brain metastases from NSCLC is regulated by glutathione peroxidase and glutathione S-transferase; among them, GPX4 and GSTM1 are overexpressed in BM subsets, and cause massive consumption of GSH in brain metastases of lung cancer." (PMID 36589232, 2022). "Moreover, GPX4 has an important function in regulating immune cells in lung cancer and other cancer types." (PMID 35620733, 2022). "GPX4 activation could weaken mitochondrial injuries induced by ferroptosis and promote lung cancer progression, while the knockdown of GPX4 could promote ferroptosis." (PMID 35835852, 2022). "Radically altered profiles of BM metabolism and protein expression compared with primary lung cancer cells were described and GPX4 and GSTM1 were identified as being responsible for the high consumption of GSH, leading to decreased chemosensitivity by negatively regulating ferroptosis." (PMID 34586745, 2021). "Therefore, we further detected the GPX4 activity with ELISA assays and investigated the correlation between GPX4 activity and cystine levels, which can sensitively reflect the level of intracellular cysteine, in the serum of lung cancer patients with BM." (PMID 34586745, 2021). "Of note, TRIB2 and PCBP2 were also important for maintaining the viability of lung cancer A549 cells via GPX4, indicating that these effects might not be restricted to liver cancer cells." (PMID 33414446, 2021). "This highlights the novelty of the present study, which suggests that blockade of Wnt/NR2F2/GPX4 axis may serve as a novel therapeutic strategy for improving the effect of chemotherapy in lung cancer BM." (PMID 34586745, 2021). "Moreover, cAMP responsive element binding protein (CREB) stimulates GPX4 transcription to inhibit ferroptosis in lung cancer cells." (PMID 34742351, 2021). "It is suggested that tumor cells that persistently exhibit multidrugs tolerance are sensitive to GPX4 inhibition by inducing ferroptosis;23 however, the specific effects of GPX4 in the chemotherapy activity, especially in secondary BM of lung cancer remain obscure." (PMID 34586745, 2021). "Here we demonstrate that GPX4 drives platinum chemoresistance in lung cancer‐derived BM by suppressing ferroptosis, indicating the potential role of selenium in promoting chemotherapy sensitivity in lung cancer patients with BM." (PMID 34586745, 2021). "In lung cancer cell lines, cell proliferation is decreased with GPX4 knockdown and this inhibition could be reversed by ferrostatin-1, the specific inhibitor of ferroptosis." (PMID 33425751, 2020). "In another study, serum selenium levels were determined in 95 patients with lung cancer and the genotypes of four selenoprotein genes (GPX1, GPX4, TXNRD2, and SEP15) were determined, demonstrating that a selenium level less than 60 μg·L−1 is associated with a higher risk of lung cancer." (PMID 30759767, 2019). "Additionally, we elucidated the specific molecular mechanism by which NLN induces ferroptosis in lung cancer cells: the knockdown of NLN inhibits the m6A modification of GPX4 mRNA, leading to the degradation of GPX4 mRNA and subsequently triggering ferroptosis in lung cancer cells." (PMID 41242017, 2025).
lung cancer (continued). "Moreover, GPX4 holds clinical significance in reducing lung cancer radiotherapy resistance." (PMID 39944353, 2024). "Ginkgetin was found to decrease the GPX4 protein levels and inhibit the antioxidant defense system of cells to cause ferroptosis in melanoma cells, whereas nobiletin reversed cisplatin resistance and increased lipid peroxidation and LIP levels in lung cancer cells." (PMID 37833746, 2023). "Importantly, our results show that etoposide upregulates GPX4 expression in NSCLC cells, suggesting that GPX4 may influence etoposide resistance in lung cancer cells." (PMID 37188685, 2023). "In addition to SLC7A11, lung cancer cell also exhibits high GPX4 expression." (PMID 36105219, 2022). "In terms of mechanism, the overexpression of STYK1 in SW900 lung cancer cell line leads to upregulation of the GPX4 expression, promotes cell proliferation, and alleviates various mitochondrial abnormalities characteristic of ferroptosis, while GPX4 knocdown performed an opposite result." (PMID 34616505, 2021). "While Lin and coworkers could induce erastin sensitivity by overexpression of TWIST or SNAI1 in primary mouse breast tumour cells, overexpression of SNAI1 in MCF7 breast or of TWIST in a lung cancer cell line did not change susceptibility to GPX4 inhibition." (PMID 34572111, 2021). "However, this is the first study to investigate whether the transcriptional regulation of GPX4 is via the Wnt/NR2F2 axis or its promoting role in the acquisition of chemoresistance by lung cancer BM." (PMID 34586745, 2021). "In order to avoid cell death, lung cancer cells use several ways to increase the induction threshold of ferroptosis, such as upregulating system xc-, increasing the antioxidant capacity, maintaining GPX4 activity, and inducing lymphoid-specific helicase to regulate lipid metabolism." (PMID 34053456, 2021). "Importantly, GPX4 is positively related to resistance of lung cancer cells to L-685458, lapatinib, palbociclib, and topotecan, indicating that targeting ferroptosis may overcome therapy resistance." (PMID 34742351, 2021). "Response to the GPX4 inhibitors RSL3, ML162, and ML210 (represented as AUC) highly correlated across the investigated lung cancer CLs." (PMID 39995872, 2025). "SLC7A11 and AIFM2 expression correlated with GPX4 inhibitors’ AUC (i.e., resistance to RSL3, ML162, and ML210) in lung cancer CLs, in agreement with the previously reported correlation in non-hematopoietic CLs in general." (PMID 39995872, 2025). "In summary, these findings demonstrate that a variety of miRNAs can modulate ferroptosis through direct targets such as GPX4, FSP1, and SLC7A11, or via upstream signaling pathways in lung cancer." (PMID 40078365, 2025). "The CPT1A/c-Myc signaling axis reduces lipid peroxide generation in lung cancer cells by suppressing ACSL4 expression and concurrently enhances resistance to ferroptosis through stimulation of the NRF2/GPX4 antioxidant pathway." (PMID 39875356, 2025). "The expression levels of GPX4 and SLC7A11 are significantly upregulated in lung cancer cells, and this upregulation correlates with the malignancy and prognosis of the tumor, making them potential therapeutic targets." (PMID 39917300, 2025). "In lung cancer, the expression profiles of GPX4 (glutathione peroxidase 4) and SLC7A11 (solute carrier family 7 member 11) are closely associated with patient prognosis." (PMID 39917300, 2025). "For instance, in colon and lung cancer cell lines, STAT3 is upregulated by iron-dependent activation of cyclin-dependent kinase 1, and it promotes the expression of GPX4, a key regulator of ferroptosis resistance." (PMID 40867343, 2025).